TBK1 (TANK binding kinase 1)
Diseases named in the same sentence as TBK1 in open-access papers (continued):
Sharing a sentence is not in itself a finding about the gene and the disease.
endometrial cancer (2 papers, 2024 to 2025). Primary or metastatic malignant neoplasm involving the endometrium (mucous membrane that lines the endometrial cavity). "We also explored the molecular mechanisms underlying the regulation of AKT/NF-κB signaling by TBK1 inhibition in endometrial cancer cells." (PMID 39744441, 2025). "In this study, we aimed to investigate the anti-cancer effects and underlying mechanisms of amlexanox, a TBK1 inhibitor, against endometrial cancer." (PMID 39744441, 2025). "Although TBK1 is closely associated with cancer progression and cell viability, its specific roles in endometrial cancer remain unknown." (PMID 39744441, 2025). "Therefore, TBK1 deficiency induced G1 cell cycle arrest in endometrial cancer cells." (PMID 39744441, 2025). "In this study, we found that amlexanox and TBK1 shRNA suppressed NF-κB phosphorylation in endometrial cancer cells." (PMID 39744441, 2025). "In conclusion, our study revealed that TBK1 inhibition exerts anti-cancer effects against endometrial cancer by regulating the AKT/NF-κB pathway." (PMID 39744441, 2025). "In this study, we aimed to investigate the effects of amlexanox and TBK1 short hairpin (sh) RNA (shRNA) on the proliferation and migration of endometrial cancer cells by inhibiting TBK1 expression." (PMID 39744441, 2025). "This study highlights the potential of TBK1 inhibition as a therapeutic strategy for endometrial cancer." (PMID 39744441, 2025). "In vitro experiments demonstrated that TBK1 knockdown or amlexanox significantly inhibited the proliferation, cell cycle progression, and migration of endometrial cancer cells." (PMID 39744441, 2025). "The present study supports these findings by demonstrating the potential of TBK1 inhibition to suppress the growth of endometrial cancer cells." (PMID 39744441, 2025). "The limited existing research underscores the need for further studies to explore the clinical relevance of TBK1 in endometrial cancer more comprehensively." (PMID 39744441, 2025). "While studies in other cancers have shown that TBK1 is a key regulator of these oncogenic pathways, there is a gap in the literature directly addressing the role of TBK1 in endometrial cancer." (PMID 39744441, 2025). "Transwell migration assay revealed that TBK1 knockdown significantly inhibited the migration of endometrial cancer cells." (PMID 39744441, 2025). "We examined the expression of phosphorylated and total TBK1 in the three endometrial cancer cell lines." (PMID 39744441, 2025). "Our findings suggest TBK1 inhibition as a promising therapeutic strategy for endometrial cancer, warranting further investigation for future translation into clinical practice." (PMID 39744441, 2025). "Collectively, these data suggest that targeting TBK1 inhibits the growth of endometrial cancer cells in vivo." (PMID 39744441, 2025). "We further investigated the metastasis of endometrial cancer cells following TBK1 knockdown." (PMID 39744441, 2025). "Moreover, we found that inhibition of TBK1 through knockdown resulted in a marked reduction in proliferation and cell cycle progression of endometrial cancer cells." (PMID 39744441, 2025). "To determine whether restoring TBK1 expression could reverse the effects of TBK1 knockdown on endometrial cancer cell proliferation, we reintroduced TBK1 into the TBK1 knockdown cells using a TBK1 expression vector." (PMID 39744441, 2025). "The effect of TBK1 on endometrial cancer cell proliferation was investigated using the WST-8 assay." (PMID 39744441, 2025). "Next, we explored whether AKT/NF-κB pathway is necessary for the anti-metastatic effects of targeting TBK1 against endometrial cancer cells." (PMID 39744441, 2025). "Here, correlation between TBK1 inhibition by amlexanox and AKT/NF-κB axis suggests that the anti-cancer effects of amlexanox are associated with its ability to suppress the proliferation and migration of endometrial cancer cells via the AKT/NF-κB pathway." (PMID 39744441, 2025).
endometrial cancer (continued). "Amlexanox shows potential for endometrial cancer targeting by targeting TBK1." (PMID 39744441, 2025). "Our study demonstrated that amlexanox and TBK1 shRNA effectively suppressed the expression of EMT-related markers and reduced the migration capacity of endometrial cancer cells." (PMID 39744441, 2025). "Overall, this study highlights the potent anti-cancer effects of amlexanox against endometrial cancer by modulating AKT/NF-κB signaling, thus providing a new avenue for the development of novel TBK1-targeting therapeutic strategies for UCEC." (PMID 39744441, 2025). "Given the effector roles of phosphorylated TBK1 and IRF3, AZD1775 was shown to activate the innate immune response signaling pathway in endometrial cancer cell lines." (PMID 38169513, 2024). "While the overall levels of TBK1 and IRF3 in HEC-1-A and HEC-1-B endometrial cancer cell lines did not change significantly, the expression levels of pTBK1 and pIRF3 increased." (PMID 38169513, 2024). "Western blotting assay found that in five endometrial cancer cell lines, compared to the control group, AZD1775 treatment did not significantly alter the expression of total TBK1 and IRF3, but notably upregulated the expression of pTBK1 and pIRF3." (PMID 38169513, 2024).
endometritis (2 papers, 2020 to 2021). An acute or chronic, usually bacterial infectious process affecting the endometrium. "Suggested that miR-19a can attenuate the activation of the NF-κB signaling pathway by targeting TBK1, thus reducing the production of inflammatory factors and inhibiting the inflammatory response of endometritis induced by LPS." (PMID 33718475, 2021).
endothelial dysfunction (2 papers, 2024 to 2025). In vascular diseases, endothelial dysfunction is a systemic pathological state of the endothelium (the inner lining of blood vessels) and can be broadly defined as an imbalance between vasodilating and vasoconstricting substances produced by (or acting on) the endothelium. "A recent study demonstrated that outer membrane vesicles (OMVs) of P. gingivalis can induce endothelial dysfunction via the Cyclic GMP-AMP synthase-stimulator of interferon genes–tank-binding kinase 1 (cGAS-STING-TBK1) signaling cascade." (PMID 39203574, 2024). "While it blocks TBK1 phosphorylation by targeting TOM70 at the mitochondria and binds NEMO (IKKγ), thereby inhibiting NF-kB activation, it seems that ORF9b plays an important role in endothelial dysfunction." (PMID 40285011, 2025).
experimental autoimmune encephalomyelitis (2 papers, 2015 to 2023). An autoimmune demyelinating disease of the central nervous system that is produced experimentally in animals by the injection of homogenized brain or spinal cord in Freund's adjuvant. "Another study also reported that TBK1 inhibitor greatly delayed the onset and decreased the severity of experimental autoimmune encephalomyelitis (EAE), and even suppressed the relapse of EAE." (PMID 37935918, 2023).
Fever (2 papers, 2017 to 2021). Body temperature elevated above the normal range. "Exogenous pathogens activate the TLRs signaling pathway constituents such as TLR4, MyD88, TBK1, IRF3, and IRAK4, and subsequently stimulate the release of pro-inflammatory cytokines which promote to progress a disease by producing fever and tissue damage." (PMID 28489052, 2017).
Herpes simplex infection (2 papers, 2021 to 2022). "Understanding these functions of TBK1, we can understand why patients with heterozygous loss-of-function TBK1 mutations are susceptible to herpes simplex infection, as observed in HSE patients." (PMID 35395857, 2022).
Huntington disease (2 papers, 2022). Huntington disease (HD) is a rare neurodegenerative disorder of the central nervous system characterized by unwanted choreatic movements, behavioral and psychiatric disturbances and dementia. "This is consistent with other findings showing that the cGAS-STING pathway activates the autophagy process through a TANK-binding kinase 1 (TBK1) independent mechanism and that cGAS is a critical regulator of inflammation and autophagy in Huntington’s disease." (PMID 36114513, 2022).
inflammatory bowel disease (2 papers, 2024 to 2025). A spectrum of small and large bowel inflammatory diseases of unknown etiology. "Its inflammatory roles extend to inflammatory bowel disease (IBD), where it compromises intestinal epithelial barrier integrity, while in antiviral defense, it potentiates IFN‐β generation through TBK1–IKKε pathway activation." (PMID 41020039, 2025).
ischemia (2 papers, 2011 to 2017). A hypoperfusion of the BLOOD through an organ or tissue caused by a PATHOLOGIC CONSTRICTION or obstruction of its BLOOD VESSELS, or an absence of BLOOD CIRCULATION. "We injected TBK1 shRNA#1 into mouse vitreous chambers 10 days before IOP elevation-induced ischemia." (PMID 28425986, 2017).
Listeria monocytogenes infection (2 papers, 2023 to 2025). "We found that ferrous iron treatment and FPN1 deficiency both attenuated Listeria monocytogenes infection-induced phosphorylation of IRF3 and TBK1 and the expression of IFN-β and proinflammatory cytokines in macrophages." (PMID 40595467, 2025).
lymph node metastasis (2 papers, 2022 to 2023). "Additionally, high TBK1 expression was correlated with large tumor, lymph node metastasis, and advanced TNM stage." (PMID 35637944, 2022). "The expression of TBK1 was increased in CRC tissues compared to the paracancer tissues, and the TBK1 expression in the CRC cases with lymph node metastasis was also significantly higher than those without lymph node metastasis." (PMID 35637944, 2022).
malignant glioma (2 papers, 2023). A grade III or grade IV glioma arising from the central nervous system. "Meanwhile, TANK and TBK1 can stabilize each other in malignant glioma, with TBK1 being crucial to TANK’s function." (PMID 38062023, 2023). "Regarding the promotion of angiogenesis in malignant gliomas, the CLOCK-BMAL1 complex was found to lead to transcriptional upregulation of periostin (POSTN), which promotes angiogenesis by activating TANK-binding kinase 1 (TBK1) in endothelial cells." (PMID 38275375, 2023).
myocardial ischemia (2 papers, 2024 to 2025). A disorder of cardiac function caused by insufficient blood flow to the muscle tissue of the heart. "Gene-metabolite interaction network analysis revealed the significant roles of key regulatory molecules such as HIF1A, adenosine, TBK1, ATP, NRAS, and EIF2AK3, in the pathogenesis of myocardial ischemia." (PMID 38818463, 2024).
non-alcoholic steatohepatitis (2 papers, 2021 to 2024). "Besides, the activation of cGAS-STING, followed by p-TBK1 phosphorylation of p62, contributed to hepato-lipotoxicity-induced ubiquitination and large protein inclusion bodies, which are markers of non-alcoholic steatohepatitis." (PMID 38312740, 2024). "A previous study from our group indicated that BX795, a TBK1 inhibitor, suppressed the expression of inflammatory cytokines, such as IL-6 and IL-10, in a nonalcoholic steatohepatitis mouse model; however, the relevant mechanism was not defined." (PMID 34858401, 2021).
oral squamous cell carcinoma (2 papers, 2018). "One preclinical cancer study involved the use of BX795, an established but not specific TBK1 inhibitor, in blocking oral squamous cell carcinoma xenograft growth." (PMID 30223576, 2018).
parasitemia (2 papers, 2018 to 2022). "Having established that cGAS-STING-TBK1 axis plays an important role in regulation of parasite burden in infected macrophages, we next asked whether a TBK1 inhibitor could be of benefit in inhibiting parasitemia in vitro and in vivo." (PMID 36405710, 2022). "Inhibition of TBK1/IKKε, an effector kinase downstream of MDA5, also significantly reduced R-NK cell control of parasitemia." (PMID 30286211, 2018). "We also examined the effect of blocking TBK1/IKKε, which is a downstream effector molecule in the MDA5 signaling pathway, on NK cell control of parasitemia." (PMID 30286211, 2018).
pneumonia (2 papers, 2022 to 2025). An acute, acute and chronic, or chronic inflammation focally or diffusely affecting the lung parenchyma, caused by an infection in one or both of the lungs (by bacteria, viruses, fungi, or mycoplasma.). "In an experimental pneumonia mouse model, TBK1 knockout (KO) mice challenged intratracheally with S. pneumoniae showed a higher mortality rate compared with wild-type mice." (PMID 36543127, 2022).
psoriasis (2 papers, 2016 to 2024). An autoimmune condition characterized by red, well-delineated plaques with silvery scales that are usually on the extensor surfaces and scalp. "In conclusion, we demonstrate that the cytokines-mediated overexpression of IFI16 contributes to the pathogenesis of psoriasis by activating the TBK1-NF-κB signaling pathway and then inducing the production of CXCL10 and CCL20 in keratinocytes." (PMID 27137868, 2016).
pulmonary arterial hypertension (2 papers, 2024). Pulmonary arterial hypertension (PAH) is a group of diseases characterized by mean pulmonary artery pressure >20 mmHg and elevated pulmonary arterial resistance leading to right heart failure. "Here, we investigate non‐canonical IKB kinases TBK1 and IKKε in pulmonary hypertension (PH) and their potential to modulate PASMC pathogenic remodeling by regulating YAP/TAZ." (PMID 38610069, 2024). "System analysis of the human pulmonary arterial hypertension lung transcriptome previously showed an activation signature for several genes in the non‐canonical IKB kinase pathway including TBK1/IKKε, and interferon regulatory factors (IRF3/7)." (PMID 38610069, 2024). "The role of AMPK in the circulatory system is not restricted to just pulmonary hypertension and vasoconstriction, but it is also implicated in the innate immune response triggered by TANK-binding kinase 1 (TBK1)." (PMID 39136185, 2024).
rectal adenocarcinoma (2 papers, 2021). "On the contrary, low levels of TBK1 expression were correlated with poorer prognosis of OS in rectum adenocarcinoma (READ), thymoma (THYM), and uterine carcinosarcoma (UCS)." (PMID 33679751, 2021).
Rotavirus infection (2 papers, 2019 to 2022). Infection with any of the rotaviruses. "Vitamin D alleviated rotavirus infection through the TBK1/IRF3 signaling pathway via directly targeting TBK1." (PMID 35462942, 2022).
triple-negative breast carcinoma (2 papers, 2016 to 2022). An invasive breast carcinoma which is negative for expression of estrogen receptor (ER), progesterone receptor (PR), and human epidermal growth factor receptor 2 (HER2).
vitiligo (2 papers, 2022 to 2023). Generalized well circumscribed patches of leukoderma that are generally distributed over symmetric body locations and is due to autoimmune destruction of melanocytes. "Another bioinformatics investigation found that TANK binding kinase 1 (TBK1) is overexpressed in vitiligo lesions,consistent with our findings." (PMID 37287971, 2023).
Yersinia infection (2 papers, 2024 to 2025). "From the KEGG map of Yersinia infection, it is evident that significant methylation changes in VAV3, TBK1, and NFATC1 subsequently influence the downstream interferon response and immune cell response." (PMID 38886689, 2024).
acute pancreatitis (1 paper, 2024). An acute inflammatory process that leads to necrosis of the pancreatic parenchyma. "It was previously reported that STING was responsible for autophagy and at the same time the STING /TBK1/IRF3 cascade was associated with acute pancreatitis development." (PMID 39702569, 2024). "In this study, knockdown of Ppm1d in rat pancreatic acinar Ficells significantly decreased Sting-Tbk1 signaling, autophagy and acute pancreatitis severity." (PMID 39702569, 2024).
adenovirus infection (1 paper, 2022). "Deletion of TBK1 reduces LC3 lipidation during adenovirus infection and restores the infectivity of an adenovirus mutant that is restricted by autophagy." (PMID 35857795, 2022).
AL amyloidosis (1 paper, 2025). AL Amyloidosis is a plasma cell disorder characterized by the aggregation and deposition of insoluble amyloid fibrils derived from misfolding of monoclonal immunoglobulin light chains usually produced by a plasma cell tumor. "The expression levels of both BDNF and phospho‐TBK1 were elevated in the CD4+ T cells from AL amyloidosis patients compared to myeloma patients." (PMID 40977494, 2025). "BDNF, calmodulin, and phospho‐TBK1 levels were decreased in CD4+ T cells from AL amyloidosis patients compared to myeloma patients." (PMID 40977494, 2025). "The mononuclear cells from AL amyloidosis patients had lower expression levels than the cells from myeloma patients for BDNF, calmodulin, phospho‐TBK1, and phospho‐ULK1 in CD4+ T cells and phospho‐GSK3β in monocytes, but higher levels of HO1 in monocytes." (PMID 40977494, 2025). "BDNF and phospho‐TBK1 were significantly correlated in CD4+ T cells from AL amyloidosis patients but not in myeloma patients." (PMID 40977494, 2025). "Additionally, BDNF and phospho‐TBK1 were tightly correlated in the CD4+ T cells from the AL amyloidosis patients but not in the cells from patients with myeloma." (PMID 40977494, 2025).
alopecia (1 paper, 2024). Hair loss usually from the scalp. "Combined loss of TBK1 and IKKε or their kinase activities in Ripk1wt/D138N genetic background caused transient alopecia, with 100% of these animals showing lack of hair at 3-4 weeks of age but fully recovering hair growth by the age of 7-8 weeks." (PMID 38167258, 2024). "To assess whether the transient alopecia was caused by loss of a keratinocyte-intrinsic function of IKKε and TBK1, we generated IkkeK38A/K38ATbk1fl/D135NK14-Crewt/tg mice that lack TBK1 kinase activity specifically in keratinocytes and IKKε kinase activity in all cells." (PMID 38167258, 2024). "Interestingly, we found that Ikke-/-Tbk1-/-Ripk1wt/D138N and IkkeK38A/K38ATbk1D135N/D135NRipk1wt/D138N, but not Tbk1-/-Ripk1wt/D138N or Tbk1D135N/D135N Ripk1wt/D138N mice, displayed alopecia before weaning with hair growth recovering almost completely by the age of 8 weeks." (PMID 38167258, 2024).
argyrophilic grain disease (1 paper, 2017). A tauopathy characterized pathologically by the presence of silver stain positive lesions called argyrophilic grains, oligodendrocytic coiled bodies, and neuronal tau-positive pretangles. "This case also had associated tau pathology consistent with argyrophilic grain disease, which has not been seen in other TBK1 mutation cases." (PMID 28229125, 2017).
ataxia telangiectasia (1 paper, 2022). Ataxia-telangiectasia is the association of severe combined immunodeficiency (affecting mainly the humoral immune response) with progressive cerebellar ataxia. "STING/TBK1/IRF3 axis is found to be activated in neurons, which induces inflammatory cytokine production and leads to neuronal death in a rat model of ataxia-telangiectasia." (PMID 35936778, 2022).
B cell lymphoma (1 paper, 2024). "When the human B cell line derived from B cell lymphoma was treated with the TBK1 inhibitors, BACH1 protein amount was increased, suggesting the universality of BACH1 protein regulation by TBK1." (PMID 38673728, 2024).
behavioral variant frontotemporal dementia (1 paper, 2025). "We present the case of a 74-year-old woman with behavioral variant frontotemporal dementia (bvFTD) linked to a pathogenic TANK-binding kinase 1 (TBK1) mutation (c.1349_1352del; p.Ile450Lysfs*15)." (PMID 40713844, 2025).
brain cancer (1 paper, 2021). A primary or metastatic malignant neoplasm affecting the brain. "Meanwhile, TBK1 expression was lower in the subtype of brain cancer." (PMID 33679751, 2021).
brain tumors (1 paper, 2020). "Notably, the most prominent and consistent areas of TBK1 activation in primary brain tumors and metastases were in cross-sections of tumor vasculature." (PMID 33013881, 2020).